TWIST1 (twist family bHLH transcription factor 1)
Diseases named in the same sentence as TWIST1 in open-access papers (continued):
Sharing a sentence is not in itself a finding about the gene and the disease.
cancer (continued). "These genes encode for proteins with well-known roles in cancer progression and normal stem cell maintenance (KIT), angiogenesis (SERPINE), and epithelial-mesenchymal transition (TWIST1, TWIST2, and ZEB2)." (PMID 31013771, 2019). "Exposure of PDX-derived cancers cells to obASCs resulted in similar expression changes of Serpine1, TWIST1, and SNAI2 (8.61 fold ± 0.19, 2.60 fold ± 1.40, 6.11 fold ± 1.15, respectively)." (PMID 31118047, 2019). "At the gene level, the expression of Twist1 is modulated by several upstream regulators through multiple pathways, depending on the cancer type and tissue context." (PMID 31383001, 2019). "As intracellular location of Twist1 expression has been reported as variable in different cancer cells, HeLa cells were employed and the cytoplasmic expression of Twist1 was found; the phenomenon was further confirmed by confocal analysis." (PMID 31138781, 2019). "TWIST1 plays a critical role in some physiological processes leading to cancer metastasis and has recently gained significant interest in cancer therapy." (PMID 31861725, 2019). "Twist1 is a key downstream regulator of p62, which suggests that targeted p62-mediated TWIST1 stabilization is a promising therapeutic strategy for cancer prevention and treatment." (PMID 31126310, 2019). "TWIST1 is involved in epithelial to mesenchymal transition and cancer metastasis and its up-regulation correlates to poor survival." (PMID 31331001, 2019). "Twist1 was able to regulate some important genes associated with EMT and cell metastasis in cancer progression." (PMID 31572802, 2019). "The current study demonstrates that SNCG knockdown abrogates TGF-β- and Twist1-induced cancer cell migration and invasion, indicating that SNCG is a novel mediator of the oncogenic TGF-β-Twist1 axis." (PMID 29795373, 2018). "Twist1 is responsible for the maintenance of cancer stem cells and the development of chemotherapy resistance." (PMID 29795373, 2018). "Highlighted Article: Pharmacological and physiological activation of AMPK promotes epithelial-mesenchymal transition in cancer cells through Twist1 upregulation and its increased nuclear localization." (PMID 29950484, 2018). "Here, we show that TGF-β induces SNCG expression by Smad-Twist1 axis, thus promoting TGF-β- and Twist1-induced cancer cell migration and invasion." (PMID 29795373, 2018). "Our clinical study strongly suggests that the sustained activation of the Twist1-Prrx1-TNC PFL is associated with a variety of fibrotic diseases and cancer stroma." (PMID 30069061, 2018). "EMT is a process frequently associated with cancer and it involves multiple regulators, including SNAI1, SNAI2, TWIST1 and ZEB1 as well as their targets." (PMID 30379847, 2018). "SIRT6 suppress cell proliferation via Twist1, which is also a key factor in the promotion of metastasis of cancer cells." (PMID 29515203, 2018). "Similar to SNCG, the basic helix-loop-helix transcription factor Twist1 acts as an oncogene in many cancers including breast cancer, hepatocellular carcinoma, pancreatic carcinoma, and neuroblastoma." (PMID 29795373, 2018). "To further investigate the biological functions that are related to the Twist1-Prrx1-TNC PFL in cancer, we analyzed the mRNA expression data of 11 types of cancers downloaded from TCGA using a gene set enrichment assay (GSEA)." (PMID 30069061, 2018). "Nevertheless, both arms lead to the activation of EMT markers which, except for TWIST1, are shared by at least two cancer types reported herein." (PMID 30111747, 2018). "In conclusion, our study uncovers a central role for AMPK in the positive regulation of EMT in cancer cells, mediated, at least in part, through Twist1 upregulation." (PMID 29950484, 2018).
cancer (continued). "Together, our data demonstrate that SNCG is a novel target of TGF-β-Smad-Twist1 axis and a mediator of Twist1-induced cancer metastasis." (PMID 29795373, 2018). "The functional connection between EMT and cancer stemness is molecularly mediated by the interdependency between Twist1 and Bmi-1." (PMID 28099910, 2017). "The notion that Twist1 is involved in cancer pathology triggered extensive analysis of Twist1 promoter hypermethylation, mRNA expression and protein level in a wide variety of tumors." (PMID 28099910, 2017). "In cancer, TWIST1 was found to repress E-cadherin and induce the expression of mesenchymal markers, such as fibronectin and N-cadherin, during EMT." (PMID 29258163, 2017). "Although the up-stream regulators of Twist1 vary largely from one cancer to another during EMT, the down-stream effectors always involve the up-regulation of N-cadherin and/or down-regulation of E-cadherin." (PMID 28099910, 2017). "At the same time, tremendous efforts have been made to modulate Twist1 as a therapeutic target for cancer treatment." (PMID 28099910, 2017). "A previous study showed that FOXD3 expression decreased cancer cell migration that was efficiently reversed by TWIST1 overexpression." (PMID 28430585, 2017). "TWIST1 overexpressing cells show a significantly elevated level of cancer stem cell-like traits, such as tumorsphere formation, ALDH1 and CD44 gene expression, and activated β-catenin and Akt pathways." (PMID 29299035, 2017). "Positive signals of Twist1 were mainly localized in the nucleus of cancer cells and stromal fibroblasts." (PMID 29029429, 2017). "To date, several reports have indicated that Twist1 is a key transcription factor that induces cancer metastasis via initiation of the EMT in a variety of cancers, including ESCC." (PMID 29029429, 2017). "In cancer cells, hypoxia was shown to reactivate TWIST1, allowing cell to disseminate to a less hostile microenvironment." (PMID 28771186, 2017). "Twist1 expression was more frequently identified in ESCC stromal fibroblasts (89.9%) than in cancer cells (33.7%) (χ2 = 113.143, P < 0.001)." (PMID 29029429, 2017). "At the gene level, the expression of Twist1 is modulated by an array of different upstream regulators via multiple pathways depending on the cancer type and tissue context." (PMID 28099910, 2017). "In vitro anchorage independent tumorigenic activity of TE11 ESCC cells was also significantly increased in cancer cells treated with CM from Twist1-expressing esophageal fibroblast (ENF8) as shown in sphere formation assay and soft agar colony formation assay." (PMID 29029429, 2017). "Previous study showed that direct binding of HIF-1α to HRE site located -83 to -79 upstream of the transcription start site of TWIST1 gene upregulates Twist1 expression in various cancer cells." (PMID 28977889, 2017). "In both the developmental and cancer contexts, TWIST1 drives epithelial to mesenchymal transition (EMT), in which cells alter their phenotype, including elongated morphology and expression of cell surface proteins, to facilitate migration and invasion." (PMID 28283022, 2017). "Of note, mitogen-activated protein kinases (ERK, JNK, and p38) are important down-stream mediators of Twist1-induced drug-resistance, but the specific effector varies from cancer to cancer." (PMID 28099910, 2017). "We showed that Twist1 expression on cancer cells induces the EMT and plays a critical role in ESCC metastasis and poor outcome." (PMID 29029429, 2017). "Recently, emerging evidences has demonstrated that Twist1 can confer chemo-resistance in various cancer cell types." (PMID 28099910, 2017). "The mRNA expression of glycolytic genes paralleled that of EMT (Snail, Slug, Twist1), suggesting the utilization of aerobic glycolysis in cancer cells that underwent EMT." (PMID 29299159, 2017). "In particular, Twist1-expressing stromal cells with a typical mesenchymal phenotype were mostly distributed in the stroma close to cancer cell nests." (PMID 29029429, 2017).
cancer (continued). "TWIST1 is a basic helix-loop-helix transcription factor which contributes to metastasis in many human cancers through promoting EMT pathway." (PMID 28460469, 2017). "Altogether, these results suggest that Twist1 is strongly associated with not only the EMT, but also cancer-associated fibroblasts, in ESCC." (PMID 29029429, 2017). "Consistent with its significance in cancer biology, Twist1 over-expression is related to high grade or invasive aggressive cancer with lymph node involvement or distant metastasis indicating therapeutic failure, recurrence, and inferior prognosis." (PMID 28099910, 2017). "Another meta‐analysis links high Twist1 or Snail1 expression with poor prognosis related to all clinical outcomes in various carcinomas such as lung and gastrointestinal tumors." (PMID 28590039, 2017). "In this study, we demonstrated that TTP inhibits the expression of Twist1 and Snail1 in human cancer cells." (PMID 26840564, 2016). "Even TWIST1’s role in cisplatin resistance is complex; TWIST1 is constitutively degraded in the epithelial cancer stem cells, widely considered to be the most drug resistant subpopulation." (PMID 27876874, 2016). "As additional examples of such, we detected early TWIST1 up-regulation and lower E-cadherin expression foci very early in BE (i.e. in BE index samples) from patients that progressed later on to cancer." (PMID 27583562, 2016). "Knockdown of Twist1 by siRNA also shows remarkable effect on reduction of apoptosis and cell death of cancer cell lines." (PMID 27027258, 2016). "In cocultures of platelets and cancer cells, Twist1 was upregulated (both mRNA and protein) (respectively)." (PMID 27074574, 2016). "In particular, Twist1 is a key regulator of EMT and a potent promoter of cancer progression and metastasis, although the underlying mechanisms are poorly understood." (PMID 27494849, 2016). "Recent studies have shown that some miRNAs can regulate Twist1 or be regulated by Twist1 in human cancers." (PMID 27027434, 2016). "TWIST1 and EMT as a whole have been linked to a growing list of cancer phenomena, including angiogenesis, stem cell maintenance, and drug resistance." (PMID 27876874, 2016). "This provides a novel mechanism for cancer development mediated by Twist1, and provides a foundation for the design of a novel inhibitor for EMT and angiogenesis." (PMID 27027258, 2016). "A growing body of studies link TWIST1 to many cancer processes outside of its traditionally studied roles in cell migration and metastasis." (PMID 27876874, 2016). "This current study examines additional cancer phenotypic impacts of TWIST1 in the context of differentiated EOC cells." (PMID 27876874, 2016). "The exogenous overexpression of Twist1 or Snail1 increases the invasive and metastatic abilities of cancer cells by promoting the down-regulation of E-cadherin and the induction of an EMT." (PMID 26840564, 2016). "Twist1, a highly conserved basic helix–loop–helix transcription factor, is a key factor in promoting metastasis of cancer cells." (PMID 27121312, 2016). "TWIST1 promotes a cancer stem cell phenotype, inhibits apoptosis and increases resistance to chemotherapy." (PMID 27661106, 2016). "Twist1 has been reported to be involved in the de-differentiation of cancer cells, leading to cell invasiveness and migration." (PMID 27835599, 2016). "Twist1, the basic helix-loop-helix transcription factor, is a potent promoter of cancer progression and metastasis." (PMID 27494849, 2016).
cancer (continued). "Other signaling pathways triggered by the interaction of platelets with cancer cells further increased the expression of Twist1 and contributed to the formation of a migratory cancer cell presumably through the induction of RAC1." (PMID 27074574, 2016). "Elevated expression of the EMT-inducing transcription factors Zeb1, Snail and Twist1 can promote EMT in multiple cancer types." (PMID 27121055, 2016). "TWIST1 promotes cancer progression by inducing epithelial to mesenchymal transition (EMT) and invadopodia formation." (PMID 27661106, 2016). "In fact, it has been shown that Twist1 induces the motile stem-like cancer cell phenotype via the activation of the Twist1-let-7i-NEDD9 axis leading to RAC1 activation." (PMID 27074574, 2016). "As a result, Twist1 and Twist2 can generate a population of self-renewing cancer stem cells through EMT." (PMID 27023622, 2016). "More directly, ectopic expression of Twist1 leads to dedifferentiation into cancer stem cells through downregulation of CD24 following EMT." (PMID 27023622, 2016). "Hypoxic conditions are similarly defined as potent inducers of Twist1 expression in cancer cells, thereby promoting cell dissemination to other friendlier environment, presumably through its role in promoting the EMT and metastasis." (PMID 26823670, 2016). "Twist1 has a wide variety of biological functions, including enhancement of the motility, invasiveness and vasculogenic mimicry formation in cancer cells." (PMID 27793033, 2016). "TWIST1 reactivation has been observed in many human cancers, where it was correlated with poor prognosis." (PMID 27661106, 2016). "Collectively, these results suggest that TTP down-regulates the expression of both Twist1 and Snail1 in cancer cells." (PMID 26840564, 2016). "In conclusion, we determined that TTP suppresses the EMT of human cancer cells through the destabilization of Twist1 and Snail1 mRNAs." (PMID 26840564, 2016). "TQ treatment also inhibited the growth and metastasis of cancer cell-derived xenograft tumors in mice but partially attenuated the migration and invasion in TWIST1-overexpressed cell lines." (PMID 26023736, 2015). "We have demonstrated that metformin-mediated antitumor activities in wild-type TWIST/N-cadherin cancer cells require TWIST1/N-cadherin/p65 signaling and are AMPK independent." (PMID 26359363, 2015). "Our study revealed that TQ can reverse this Cadherin balance by down-regulating TWIST1 in cancer cells." (PMID 26023736, 2015). "Some studies have indicated that knockdown of TWIST1 in cancer cell lines inhibits cancer initiation progression and metastasis." (PMID 26023736, 2015). "Consistent with our observation, TWIST1 has been reported to be over-expressed in several cancers including OSCC." (PMID 26214683, 2015). "In the current study, SATB1 was identified to expand the cancer stem cell population, accompanied by the activation of the Notch signaling pathway, which promotes cancer stem cell self-renewal and the expression of the Snail1 and Twist1 genes that drive EMT." (PMID 25586771, 2015). "Promoter methylation of TWIST1 gene has been reported in several cancers, especially in distant metastasis." (PMID 26023736, 2015). "The results of this study thus showed that TQ down-regulates TWIST1 in cancer cells, and also regulates the Cadherins (up-regulation of E-Cadherin and down-regulation of N-Cadherin), concomitantly with its antimetastatic activity." (PMID 26023736, 2015). "Ectopic expression of TWIST1 up-regulated N-cadherin/NF-kappaB signaling and led to more resistant cancer cells." (PMID 26359363, 2015). "The TWIST1 transcription factor activates EMT in cancer cells and activates several target genes that promote cellular dedifferentiation and cell mobility." (PMID 25759817, 2015). "In high-grade budding cancers, significant inverse correlations between TWIST1 methylation and TWIST1 stromal expression was observed (high-grade r = –0.4; p < 0.001)." (PMID 25528769, 2015).
cancer (continued). "TWIST1 has been regarded as an oncogene, and knockdown of TWIST1 is expected to be beneficial against cancer." (PMID 26023736, 2015). "The exogenous over-expression of Twist1 increases the invasive and metastatic abilities of human cancer cells by promoting the down-regulation of E-cadherin and the induction of EMT." (PMID 26110787, 2015). "Our study indicates that TWIST1 along with its down-stream proteins, especially Cadherins are the novel targets of TQ treatment in cancer cells." (PMID 26023736, 2015). "Alterations of TWIST-1 expression are often seen in solid tumors and contribute to tumorigenesis and cancer progression." (PMID 26023795, 2015). "We tested the ability of the YTZ3-15-delivered siRNA to knock down TWIST1, reduce expression of EMT-related target genes, and alter the phenotypic characteristics associated with cancer cell migration/invasion." (PMID 25759817, 2015). "Most importantly, Twist1 is an important E-cadherin repressor (34, –, 37), and the overexpression of Twist1 in several cancers have been well documented (38, –, 41)." (PMID 25847239, 2015). "For the investigation of the expression of TWIST1 and its downstream proteins, after 6 h of TQ treatment (5 μM), the mRNAs and after 48 h of TQ treatment, the proteins were extracted from cancer cell lines." (PMID 26023736, 2015). "The transcription factor TWIST1, along with SNAIL1, SLUG and ZEB1, plays the major role in EMT-associated metastasis in cancer cells." (PMID 26023736, 2015). "Several groups have shown that Twist1 was re-activated by treatment with a de-methylation drug, 5-aza-2’-deoxycitidine (5-aza-dC), in cancer cells." (PMID 26695186, 2015). "Previous studies have revealed that HMGA2, SALL4 and Twist1 are involved in cancer stem cell self-renewal in different cell types." (PMID 25919570, 2015). "Zeb1/2, Snai1/2 and Twist1 have recently been described as targets of the Fbxo45 containing ubiquitin ligase complex in cancer cell lines." (PMID 26068074, 2015). "In recent years, emerging evidences suggest that TWIST-1 enhances the acquired resistance of cancer cells to drug." (PMID 26023795, 2015). "Treatment of TQ in TWIST1 knockdown cancer cells induced inhibition activity of migration and invasion." (PMID 26023736, 2015). "Together, these results demonstrate that TQ treatment inhibits TWIST1 promoter activity and decreases its expression, leading to the inhibition of cancer cell migration, invasion and metastasis." (PMID 26023736, 2015). "These biological processes are consistent with known Twist1 functions during embryogenesis and in cancer cells." (PMID 25262113, 2014). "Twist1 expression is normally silenced after embryonic development, but expression is reactivated during disease, including cancer." (PMID 25262113, 2014). "Emerging evidence suggests that TWIST1 plays an important role in the chemoresistance of cancer cells." (PMID 25238494, 2014). "TWIST1 overexpression has been reported in a variety of cancers, and many observations have highlighted the role of TWIST1 in promoting cancer cell EMT and metastasis." (PMID 25238494, 2014). "Previous studies confirmed that overexpression of Twist1 was identified in multiple types of cancer in humans, with numerous damaging consequences, including promoting the immigration and invasion of cancer cells, and decreasing sensitivity to chemotherapy." (PMID 24805866, 2014). "TWIST1 itself is also known to regulate the expression of several miRNAs, many of which are cancer-related." (PMID 23741524, 2013). "Ardent investigation and flux of newly published papers suggest that miR-200 families impact cancer invasiveness by collaborating with other molecules, such as Notch, Twist1 and PLCγ1." (PMID 23372687, 2013). "Upregulation of the proto-oncogene Twist1 is highly correlated with acquired drug resistance and poor prognosis in human cancers." (PMID 23741524, 2013).